TNF (tumor necrosis factor)
Diseases named in the same sentence as TNF in open-access papers (continued):
Sharing a sentence is not in itself a finding about the gene and the disease.
melanoma (continued). "In human and canine melanoma cells, a recent study has shown a new apoptosis-inducing mechanism of 5-aza-dC through demethylation and induction of cytotoxic cytokines such as TNF-α in in vitro and in vivo experiments, suggesting a potential therapeutic agent for human and canine melanomas." (PMID 33194754, 2020). "Interestingly, in the presence of IFNγ and TNFα melanoma cells can also upregulate TGFB, IL10, VEGFA, and VEGFC genes, which can further modulate the immunosuppressive phenotype of TAMs." (PMID 32793228, 2020). "Interestingly, compounds binding to the FKBP51FK1 domain—namely FK506, Rapamycin, SAFit1 and SAFit2—inhibited TNF-α induced IκB-α degradation in human melanoma cells (A375)." (PMID 30669684, 2019). "In addition, treatment with N-glycans derived from theses glycosaminoglycan increased activities of TIMP-2 in HMVEC cells pretreated with TNF-alpha and in melanoma cells, suggesting that they had anti-inflammatory and anticancer activities." (PMID 30611221, 2019). "Interestingly, poly-functionality was observed also in a clinical study, where a personalized vaccine delivered as an RNA for melanoma patients showed poly-functional CD8+IFN-γ+TNF-α+ immune responses." (PMID 30764846, 2019). "Moreover, lineage tracing of melanoma cancer stem cells exposed to a transient TNF signal showed that these cells expanded and increased in stemness in response to the TNF cue and that the PI3K/AKT pathway was necessary for this expansion." (PMID 31118427, 2019). "Fibroblast activation protein α (FAPα) vaccine in combination with curcumin was shown to significantly inhibit TNFα-induced EMT in melanoma cells by targeting indolamine-2,3-dioxygenase, inhibit tumor growth and prolong the survival of mice implanted with melanoma cells." (PMID 31547193, 2019). "It is noteworthy that although TNFα promoted BRAF ubiquitination in BRAFV600E-expressing 1205Lu melanoma cells, the treatment only moderately affected MEK/ERK activities, which is consistent with the results that p-MEK/p-ERK levels were insensitive to ITCH knockdown." (PMID 31015455, 2019). "As expected, CSPG4-expressing A375M melanoma cells evoked TNF production by CSPG4-CAR T cells." (PMID 31195686, 2019). "Moreover, melanoma exosomes were able to hinder the induction of the cell death response commonly triggered by TNFα." (PMID 31681332, 2019). "In a mouse melanoma model, mice deficient for MIP-1α/β had increased tumour growth as well as a higher incidence of metastases, also associated with lower local production of IFNγ, TNFα and IL-644." (PMID 30872676, 2019). "The high systemic toxicity associated with TNF treatment hampered the transposition of such a treatment to the clinic until two research teams developed procedures whereby high concentrations of TNF were perfused in isolated limbs of patients with melanoma or sarcoma." (PMID 31417576, 2019). "Exposure to TRIM59-/--M2 macrophage supernatant promoted migration and invasion of B16 melanoma cells, and inhibitory experiments indicated that overexpression of TNF-α by TRIM59-deficient M2 macrophages and activation of ERK, and perhaps PI3K, signaling in B16 melanoma cells mediated these effects." (PMID 31600735, 2019). "Moreover, the binding of endogenous BRAF with 14–3–3 proteins was attenuated after melanoma cells were treated with TNFα, which were shown to activate JNK/ITCH to facilitate BRAF ubiquitination." (PMID 31015455, 2019). "Soluble PD-L1 may result from alternative variants of the PD-L1 transcripts and cytokine treatment with IFN-α, IFN-γ, or TNF-α has been shown to increase secretion of sPD-L1 as well as expression of cell surface PD-L1 in melanoma cell lines." (PMID 31192215, 2019). "Moreover, our team showed that TNF production in mouse melanoma triggered TNF-R1-dependent activation-induced cell death (AICD) of CD8+ TILs." (PMID 31417576, 2019).
melanoma (continued). "Intriguingly, accompanied by reduced 14–3–3 binding, BRAF p-S365 phosphorylation was significantly downregulated in melanoma cells treated with TNFα, suggesting that K27-linked ubiquitination of BRAF may facilitate the dephosphorylation of p-S365." (PMID 31015455, 2019). "Indeed, the secretion of tumor-necrosis-factor α (TNF-α) and IL-12 by dendritic cells is inhibited when they are co-cultured with melanoma, cells either BRAF mutated or wild-type." (PMID 31762942, 2019). "The effectiveness of MAPK cascade-targeting therapies to treat patients with BRAF-V600E-mutant melanomas has been limited by a range of resistance mechanisms that may be driven by the tumor necrosis factor (TNF)." (PMID 30400822, 2018). "Effects of TNF on transcripts differentially expressed in A357 vs SK-MEL-28 human melanoma cells." (PMID 30591049, 2018). "Concerning GT genes involved in ganglioside biosynthesis, a functional NFκB binding site at -777/-762 pb upstream the ATG was shown to be essential for ST8SIA1 transcription in melanoma cells and inflammatory cytokines including TNF and IL-6 enhanced GD3S gene expression in melanocytes." (PMID 29698439, 2018). "Finally, selective sequestration of both recombinant and macrophage-derived TNF using INB03 effectively prevented acquisition of resistance to MAPKi by BRAF-V600E mutant melanoma cell lines in vitro." (PMID 30400822, 2018). "Therefore, we intended to validate the role of TNFα signaling on ceramide generation pathway in PKCδ silenced A375 human melanoma cells." (PMID 30701020, 2018). "The hypothesis that TNF-α may be an intrinsic crucial player in melanoma growth and aggressiveness was further tested by inhibiting the TNF secretion through a chimeric monoclonal antibody (INFLIXIMAB-IFX)." (PMID 30591049, 2018). "Interestingly, there is a phase Ib clinical trial evaluating the safety and efficacy of anti-TNFα given concomitantly with ipilimumab and nivolumab in patients with advanced melanoma (NCT03293784)." (PMID 30305177, 2018). "In one melanoma case, diffuse T-cell infiltration following TCR-engineered ACT was associated with tumor necrosis factor (TNF)-α-mediated immunosuppressive dedifferentiation, manifested as a gain of the neural crest stem cell marker NGFR and loss of melanocytic markers." (PMID 30466478, 2018). "Recombinant TNF was used to induce MAPKi resistance in melanomas." (PMID 30400822, 2018). "Similarly, a previous study revealed that in the blood of melanoma cell-infiltrated livers, TNF-α and IL-1β were inhibited, and IL-18 augmentation was prevented by treatment of resveratrol." (PMID 30670927, 2018). "Hence our data suggests that the TNFα mediated signaling is also operational to increase apoptosis by ceramide generation in PKCδ silenced human melanoma cells." (PMID 30701020, 2018). "The role of TNF-dependent pathways in melanoma cells growth and malignant phenotype proposed in the current study confirms previous data carried out in similar cellular models as well as the controversial role of TNF in cutaneous melanoma." (PMID 30591049, 2018). "Tumor necrosis factor-α (TNF-α) mediates the de-differentiation of melanoma cell." (PMID 30139382, 2018). "However, in contrast to TNF, which has been shown to directly prevent melanoma cell death in the presence of BRAF signaling inhibition, IL-1β cannot prevent cell death when BRAF signaling is inhibited." (PMID 28450382, 2017). "Indeed, as reported by others, TNF can trigger melanoma dedifferentiation as well as expression of the Ezh2 histone methyltransferase and the CD73 ectonucleotidase in melanoma cells, all of those events conferring resistance to immunotherapy." (PMID 29273790, 2017). "Angiogenic factors including VEGF, TGF-β, and TNF-α have been previously shown to play an active role in priming the lymphoid microenvironment for melanoma migration; however, the events responsible for inducing secretion of these factors are largely unknown." (PMID 28424693, 2017).
melanoma (continued). "In tumors from CD8-deficient mice, TNF and IFN-γ mRNA levels remained low under both control and anti-PD-1 conditions, demonstrating that CD8+ T cells are required for potent production of TNF and IFN-γ in this melanoma model." (PMID 29273790, 2017). "Consequently, TNF blockade/deficiency prevents PD-L1 and TIM-3 expression as well as AICD in CD8+ TILs, overcoming the resistance to anti-PD-1 in experimental melanoma." (PMID 29273790, 2017). "As compared to untreated mice, anti-TNF alone slightly inhibited B16K1 melanoma growth." (PMID 29273790, 2017). "Thus, Ostyn and coworkers using an inducible H2B-GFP tracing system have shown that TNF-α increases the sub-population of quiescent or slow-cycling melanoma stem-like cells at the level of melanospheres." (PMID 29156643, 2017). "To test whether MALT1 is required for NF-κB activation in melanoma cells, we treated A2058 and A375 cells with 50 ng/ml tumor necrosis factor-α (TNFα) for 15 min." (PMID 28759024, 2017). "In addition, melanoma cells are fragilized in presence of MelanA-specific CTLs or their cytokines IFNγ and TNFα." (PMID 27625650, 2016). "Interestingly, the increase in expression of these factors by MSC stimulation with IFN-γ + TNF-α was similar to the changes induced in MSCs by melanoma activated TIL5." (PMID 27211104, 2016). "Studies focused on the reciprocal interactions of melanoma and immune cells demonstrated that microenvironment-derived tumour necrosis factor (TNF)-α might induce dedifferentiation of the melanoma cells." (PMID 27175588, 2016). "M1 cells play a great role in melanoma as they promote inflammatory response mediated by TNF-a." (PMID 27706081, 2016). "Regulation by TNF‐α can induce MITF expression in melanoma cells through IKK/NFkB signalling." (PMID 25818589, 2015). "Furthermore, a recent report identified TNFα/NF-κB pathway as a potent stimulator of CD271 in melanoma cells." (PMID 27462428, 2015). "Clinical trials are necessary to evaluate the therapeutic value of TNF blockade strategy in melanoma patients and define the eligibility criteria such as (i) TNF expression in melanoma biopsies, (ii) pre-existing CD8+ T cell infiltration, (iii) MHCI expression by melanoma cells." (PMID 26622939, 2015). "Similarly to A375 cells, SAN melanoma cells depleted of FKBP51 showed impaired IKK kinase activity following TNFα stimulation, and a reduced NF-κB activation, in comparison with SAN control cells." (PMID 26101251, 2015). "To address the global relevance of c-Jun induction in the context of MITF loss for inflammatory hyperresponsiveness of melanoma cells, we performed co-knockdown experiments with siRNAs against MITF and c-JUN in the absence or presence of TNF-α and analysed the transcriptional changes by microarray." (PMID 26530832, 2015). "Re-analysis of the gene expression data from our TNF-stimulated melanoma cell line panel consistently revealed that suppression of MITF mRNA significantly correlated with the reciprocal induction of c-JUN mRNA, but obviously this switch was variable among the different cell lines." (PMID 26530832, 2015). "Targeting either TNF or TNF-R1 may reduce the death of activated CD8+ TILs in patients affected with melanoma and thus may constitute an emerging immunotherapy to enhance CD8+ T cell-dependent immune response against melanoma." (PMID 26622939, 2015). "Notably, we found that curcumin inhibits both basal and IFN-γ-induced IDO expression and simultaneously represses TNF-α-induced EMT in B16 melanoma cells." (PMID 26305550, 2015). "Thus, in melanoma patients, IL-6 increases with stage, as does TNF-alpha and IL-8; IL-6 being positively correlated with other serum markers tested in our patients, like S100 and MIA31,94." (PMID 32309563, 2015).
melanoma (continued). "This suggests that curcumin suppresses TNF-α-induced EMT in B16 melanoma cells." (PMID 26305550, 2015). "Furthermore, our results indicate that CD271 expression and BRAFi resistance are supported by TNFα/NF-κB pathway activation, providing a pharmacologically actionable target to overcome drug resistance in melanoma therapy." (PMID 27462428, 2015). "Adenovirally expressed TIMP3 stabilzes tumor necrosis factor receptor-1 (TNF-R1), FAS, and TNF-related apoptosis, inducing ligand receptor-1 (TRAIL-R1) on melanoma cell surface, sensitizing these cells to apoptosis induced by TNF-α, anti-FAS-antibody and TRAIL." (PMID 26116372, 2015). "In addition, downregulation of FAN in B16 melanoma cells decreases TNF-induced B16 melanoma motility and invasion." (PMID 26622939, 2015). "FK506, indeed, reduced TNFα-stimulated IKK activity in A375 melanoma cells." (PMID 26101251, 2015). "Moreover, experimental models of invasion and metastasis have shown that TNF-α promotes melanoma dissemination." (PMID 25120672, 2014). "Finally, human recombinant TNF (hrTNF) in combination with Melphalan is being used for treatment of advanced melanoma and inextirpable soft tissue sarcomas using isolated limb perfusion." (PMID 24664144, 2014). "Furthermore, adoptive transfer of STZ-diabetic P14 CD8+ effector cells showed an insufficient recruitment to the B16.gp33 melanoma and inadequate production of perforin, granzyme B and TNFα determined by immunohistochemistry in the tumor milieu." (PMID 25390652, 2014). "TNF-α is a well known cytokine which can induce apoptosis in a range of cancer cells, and now it is used in the clinic as a regional treatment of locally advanced soft tissue sarcomas and metastasis melanomas to avoid of amputation limbs." (PMID 24926661, 2014). "Little is known concerning the effect of TNF on the melanoma SC compartment." (PMID 25223735, 2014). "The NFκB inhibitor did not affect the TNF-induced upregulation of GFPhighABCB5high melanoma SCs, demonstrating that this effect is linked to AKT rather than NFκB activation." (PMID 25223735, 2014). "Unfortunately, only in rare cases clinical activity was seen and severe adverse events have been a major hurdle, and to date TNF-α in melanoma is only used as a ‘facilitator’ to increase penetration of chemotherapeutic agents in the settings of single limb perfusion of in-transit metastases." (PMID 24920406, 2014). "Furthermore, the p38 MAPK inhibitor SB203580 was revealed to suppress MCP-1 production in melanoma cells, and as with AH23848, SB203580 abrogated MCP-1 upregulation caused by TNF-α or exogenous PGE2." (PMID 23420676, 2013). "TNF-α release was analyzed in NK-melanoma cell co-cultures in the presence of ipilimumab." (PMID 23634660, 2013). "Of interest is tumor necrosis factor-α (TNFα), a proinflammatory cytokine, which may be involved in anti- or pro-tumor activities in melanoma development." (PMID 23965971, 2013). "Furthermore, we show that ADCC and TNF-α secretion are triggered in FcγRIIIA+ lymphocyte subsets upon Ipilimumab interaction with CTLA-4 on melanoma cells." (PMID 23634660, 2013). "Furthermore, NK cells in the presence of Ipilimumab interacting with CTLA-4+ melanoma cells can release TNF-α." (PMID 23634660, 2013). "TNF-α was released upon interaction of NK cells with CTLA-4+ melanoma cell lines." (PMID 23634660, 2013). "Therefore, further investigation into the signaling intermediates regulating TNFα secretion in UV-irradiated melanocytes and melanoma cells is warranted." (PMID 23965971, 2013). "Altogether, these results suggest that TNF-α released from Cl-IB-MECA-treated CD8+ T cells or after Cl-IB-MECA administration induced LCs activation/influx in the melanoma tissue, which could, in turn, facilitate the T cell responses in vivo." (PMID 23028986, 2012).
melanoma (continued). "Our results revealed that the pro-angiogenic, AA-derived eicosanoids PGE2, 12-HETE, and 15-HETE, as well as the key inflammatory factors interleukin-6 (IL-6) and tumor necrosis factor α (TNF-α), were dramatically reduced in B16 melanoma and LLC tumors treated with D6D-RNAi or SC-26196." (PMID 23112819, 2012). "Ibuprofen significantly reduced TNF-α-stimulated migration of melanoma cells." (PMID 24212647, 2011). "It is possible that different mechanisms may be involved in UV-induced TNF-α release in melanoma and melanocyte cells and as such these test compounds may inhibit certain mechanisms but not others resulting in varying efficacy of inhibition." (PMID 21961050, 2011). "Similarly, in vitro and in vivo studies using the TNF-α resistant melanoma cell line B16BL6 demonstrated that IFN-γ sensitizes cancer cells to the effects of TNF-α, inducing necrosis and tumor response, which were previously absent." (PMID 22036896, 2011). "This is consistent with an earlier study that demonstrated that vitamin D3 repressed IL-8 promoter activity induced by TNF-α in human melanoma cell line by 50% compared to 30% inhibition by dexamethasone, as well as TNF-α-induced IL-8 release and IL-8 mRNA level." (PMID 21765616, 2011). "Since sHLA-E release by melanoma cells is mainly matrix metalloproteinase-dependant, TNF-α effect on HLA-E production could be due to the ability of TNF-α to promote matrix metalloproteinase expression." (PMID 21712991, 2011). "Interestingly, our study showed that about 15% of polyclonal melanoma infiltrating DP T cells produce TNF-α in response to autologous tumor cells, demonstrating the frequent anti-tumor reactivity of this new sub-population." (PMID 20052413, 2010). "Supraphysiologic doses of TNF have been used to treat melanomas, suggesting that anti-TNF therapy may be disadvantageous." (PMID 20535785, 2010). "Interestingly, a high proportion of these cells produced TNF-α in response to autologous melanoma cell lines." (PMID 20052413, 2010). "Moreover, the mean percentage of cells producing TNF-α in response to autologous melanoma was superior in DP T cells than in SP CD8 T cells (14.7% versus 4.7%)." (PMID 20052413, 2010). "Finally, higher proportions of tumor-reactive T cells co-expressing CCL4, IFN-γ, and TNF-α were detected in melanoma patients with favorable clinical responses to α-CTLA-4 treatment." (PMID 21203522, 2010). "An observational study from the National Data Bank for Rheumatic Diseases also found an increased risk of melanoma in patients treated with anti-TNF therapy, although the overall risk of malignancy was not increased." (PMID 20535785, 2010). "However, the mechanism responsible for selective inhibition of MMP-2, MMP-9 and TNF-α expression in HB-19 treated melanoma cells and tumors remains to be elucidated." (PMID 20573279, 2010). "Probably, the pro-inflammatory state which has been described in old ages, may represent a stimulus for the production of TNF-α in γδ T cells from aged subjects, differently with what occurs in old melanoma patients." (PMID 15686597, 2005). "In this study, we examined whether blockade of TNF could reduce metastasis in the murine B16F10 melanoma model and compared the efficacy of anti-TNF monoclonal antibodies and the TNF autovaccination technology in reducing metastasis." (PMID 15026813, 2004). "In the current study, we extend this work investigating to what extent TNF-α might stimulate melanoma invasion by promoting cell migration and whether α-MSH is also inhibitory." (PMID 15054471, 2004). "In the current study, TNF-α activated NFκB/p65 in over 80% of all melanoma cells within 60 min." (PMID 14612916, 2003). "The current study continues this work asking the question of whether TNF-α promotes melanoma invasion through fibronectin via activation of melanoma proteolytic enzymes." (PMID 12966436, 2003). "A ‘scratch wound’ model was used to examine the effect of TNF-α on melanoma cell migration." (PMID 12966436, 2003).